RNU6-556P (RNA, U6 small nuclear 556, pseudogene)
Gene: Small nuclear RNA gene on chromosome 5 (156,814,130 to 156,814,234, forward strand). Ensembl gene ENSG00000199468.
Homologues: Orthologues: chimpanzee U6 (98% identical), macaque U6 (91% identical), rabbit U6 (91% identical), guinea pig U6 (82% identical), tropical clawed frog U6 (81% identical). Paralogues in human: RNU6-1145P (90% identical), RNU6-38P (90% identical), RNU6-15P (89% identical), RNU6-188P (89% identical), RNU6-209P (89% identical), RNU6-20P (89% identical), RNU6-312P (89% identical), RNU6-411P (89% identical), RNU6-574P (89% identical), RNU6-1 (88% identical), RNU6-11P (88% identical), RNU6-128P (88% identical), and 1288 more.